MMP7 (matrix metallopeptidase 7)
Diseases named in the same sentence as MMP7 in open-access papers (continued):
Sharing a sentence is not in itself a finding about the gene and the disease.
Sepsis (5 papers, 2014 to 2025). Sepsis is defined as life-threatening organ dysfunction caused by a dysregulated host response to infection. "The MMP-7/EpCAM ratio differentiated NEC from sepsis and healthy controls with high diagnostic accuracy, although the study was limited by a small sample size and lack of information on how neonates were diagnosed for sepsis." (PMID 30094238, 2018). "Loss of MMP7 could potentially attenuate sepsis-induced kidney injury through decreased activation of NLRP3 and NLRP6 inflammasomes in the kidney." (PMID 40341670, 2025). "We hypothesized that global loss of MMP7 would attenuate sepsis-induced ALI and systemic inflammation." (PMID 40341670, 2025). "Although not significant, the modest numerical reductions in KIM-1 and NGAL in septic MMP7KO compared to septic WT mice raises the possibility that MMP7 could play a small role in sepsis associated kidney injury." (PMID 40341670, 2025). "In summary, our findings address the role of MMP7 in the context of a clinically relevant model of sepsis-induced ALI." (PMID 40341670, 2025). "In clinical and animal studies, MMP-7 is considered to be more important in eliminating infectious agents through immune activation in sepsis patients." (PMID 36142454, 2022). "Together, these data suggest a potential role for MMP7 in the pathogenesis of sepsis-induced ARDS." (PMID 40341670, 2025). "The increased expression of cyclin D1, VEGF, and MMP7 in our study supports the importance of Wnt signaling in perpetuating lung inflammation and provides insights into the early development of a pro-fibrotic response during sepsis-induced ARDS." (PMID 25331176, 2014). "We extended our in vitro findings by confirming that collagen synthesis and the main target gene products of this pathway (WNT5A, MMP7) increased in a clinically relevant model of sepsis-induced lung injury and in lungs from patients who died with severe sepsis and ARDS." (PMID 25331176, 2014). "Thus, we hypothesized that global loss MMP7 would attenuate sepsis-induced ALI and non-pulmonary organ dysfunction through reduced systemic and pulmonary inflammation." (PMID 40341670, 2025). "The association of the MMP-1 (-1607 1G/2G) SNP and sepsis might be due to linkage disequilibrium with the MMP-13 SNP because the MMP-13 and MMP-1 genes are both located in the same cluster of the chromosome 11q22-23 along with the MMP-3, MMP-7, MMP-8, MMP-10, MMP-12, and MMP-20 genes." (PMID 24833564, 2014). "Genetic deletion of MMP7, as confirmed by non-detectable lung or kidney MMP7 mRNA expression across control and septic treatment groups, did not alter any markers of physiological dysfunction for sepsis-induced ALI." (PMID 40341670, 2025). "In conclusion, MMP7 is not essential for the development or resolution of sepsis-induced ALI in this model and likely plays a limited role in the condition." (PMID 40341670, 2025). "Based on these data, we conclude that MMP7 has a limited role in the pathogenesis of murine sepsis-induced ALI and there may be sex differences in inflammatory responses to sepsis." (PMID 40341670, 2025). "One possible explanation for these findings is that other MMPs may compensate for the lack of MMP-7 in the current model of sepsis-induced ALI." (PMID 40341670, 2025). "Notably, the absence of MMP7 does not significantly reduce sepsis-induced systemic, lung, or kidney inflammation, or affect the severity of lung or kidney injury severity of sepsis-induced kidney injury." (PMID 40341670, 2025). "Our findings show that MMP7 does not play a significant role in ALI induced by polymicrobial abdominal sepsis, with MMP7KO mice showing similar sepsis-induced pathophysiology compared to WT mice." (PMID 40341670, 2025).
serous ovarian cancer (5 papers, 2008 to 2025). "The highest SE for the serous ovarian cancer patient total group was achieved by MMP-7 (94%), which was the only MMP that slightly overtook CA125 (93%)." (PMID 40565125, 2025). "For MMP7 rs17098236, the combined age- and site-adjusted estimate from the log additive model suggested an association with serous ovarian cancer but the point estimates were not in the same direction as those obtained in discovery analysis (0.84 vs.1.19)." (PMID 20628624, 2010). "We therefore intend to proceed with evaluation of MUC16, WFDC2, MSLN and MMP7, all of which have sensitivity >30% at 98% specificity in detection of clinically apparent serous cancers, beginning with analysis of serum specimens collected months to years prior to diagnosis of serous ovarian cancers." (PMID 18612378, 2008). "Of the MMPs tested, MMP-7, MMP-26, and MMP-10 have the highest potential in diagnostics of serous ovarian cancer patients." (PMID 40565125, 2025). "Furthermore, a significant increase in the expression levels of MMP7, MMP9, and MUC16 genes was observed in the serous ovarian carcinoma groups (LGSOC and HGSOC) when compared to the BSC group." (PMID 37569592, 2023). "Notably, a significant downregulation of miR-214-3p and miR-424-5p, which potentially regulate MMP7 and/or MUC16, was observed in the groups of serous ovarian carcinomas (LGSOC and HGSOC)." (PMID 37569592, 2023). "In addition, increased expression levels of MMPs, including MMP-2, MMP-7, and MMP-9, as well as TIMPs, including TIMP-1 and TIMP-2, were observed in mucinous ovarian cancer compared with those in serous ovarian cancer." (PMID 32197606, 2020).
type 2 diabetes (5 papers, 2014 to 2024). "In hypercholesterolemic patients with type 2 diabetes, elevated MMP-7 and MMP-8 concentrations were reduced by atorvastatin, along with their ratios to TIMP-1, through suppression of inflammatory mediators." (PMID 39200884, 2024). "The study demonstrated that the level of MMP-7 was increased in patients with type 2 diabetes with diastolic dysfunction and in those with microalbuminuria." (PMID 39335666, 2024). "In conclusion, this study shows that canagliflozin treatment decreases the plasma concentration of TNFR1, IL-6, MMP7 and FN1 in individuals with type 2 diabetes and elevated albuminuria." (PMID 31001673, 2019). "We also found that in type 2 diabetes, treatment with an angiotensin receptor antagonist tended to reduce urine AGT concentration, but not urine MMP‐7 or gremlin‐1." (PMID 24793984, 2014). "We also find a decrease in urine AGT, but not MMP‐7 or gremlin‐1, in response to RAS inhibition in people with type 2 diabetes and DKD, potentially reflecting therapeutic response." (PMID 24793984, 2014).
ulcers (5 papers, 2010 to 2023). "In patients with the two combined factors, ulcer location and MMP-7 and MMP-9 intensities are similar to NSAID use." (PMID 22645431, 2012). "As such, this study surveyed if the H. pylori dupA genotype and certain SNP genotypes of MMP-3, MMP-7, MMP-9, TIMP-1, and TIMP-2 predispose H. pylori-infected Taiwanese patients to ulcer risks." (PMID 20707923, 2010). "This study investigated if the H. pylori dupA genotype and certain host single nucleotide polymorphisms (SNPs) of matrix metalloproteinases (MMPs) and their inhibitors (TIMPs), including MMP-3, MMP-7, MMP-9, TIMP-1 and TIMP-2, might correlate with ulcer risk of H. pylori-infected Taiwanese patients." (PMID 20707923, 2010). "Matrix metalloproteinase-7 gene (MMP7) is highly expressed in intestinal tissues of patients with enteritis, especially in intestinal epithelial cells at the edge of ulcers, so it is a common marker of inflammation." (PMID 37927593, 2023). "On the other hand, epithelial cells on the margins of ulcers most often produce MMP-7 This study indicates that MMP-7 plays roles in the re-creation of epithelium after injury." (PMID 38203373, 2023). "H. pylori-infected gastric ulcers express higher MMP-7, MMP-9, and TIMP-1 than NSAID-related ulcers." (PMID 22645431, 2012).
carotid atherosclerosis (4 papers, 2014 to 2025). A thickening and loss of elasticity of the walls of carotid arteries that occur with formation of atherosclerotic plaques. "(iv) During the follow-up of patients with carotid atherosclerosis, high plasma levels of MMP-7 were independently associated with total mortality." (PMID 24400123, 2014). "Finally, we report that high plasma levels of MMP-7 in patients with carotid atherosclerosis are independently associated with mortality during follow-up." (PMID 24400123, 2014). "Our findings further support a link between MMP-7 and plaque instability in patients with carotid atherosclerosis, potentially reflecting macrophage and matrix degrading mechanisms." (PMID 24400123, 2014). "Our major findings were (i) Patients with carotid atherosclerosis had markedly increased plasma levels of MMP-7 compared to healthy controls, with particularly high levels in patients with recent symptoms (i.e., within the last 2 months)." (PMID 24400123, 2014). "Patients with carotid atherosclerosis (n = 182) had markedly raised plasma levels of MMP-7 compared with healthy controls (n = 23) (1.96 ng/ml versus 0.89 ng/ml, medians; p<0.001)." (PMID 24400123, 2014). "In the present study we extend these previous findings by showing increased MMP-7 levels systemically as well as within the atherosclerotic lesion in patients with carotid atherosclerosis with the most recent symptoms (i.e., within two months)." (PMID 24400123, 2014). "Importantly, however, plasma levels of MMP-7 were significantly raised in patients with carotid atherosclerosis as compared with healthy controls also after adjusting for age (p<0.001)." (PMID 24400123, 2014). "Our findings suggest that MMP-7 could contribute to plaque instability in carotid atherosclerosis, potentially involving macrophage-related mechanisms." (PMID 24400123, 2014). "Nonetheless, our findings suggest that MMP-7 could contribute to plaque instability in patients with carotid atherosclerosis, potentially involving macrophage-related mechanisms." (PMID 24400123, 2014). "Our findings show up-regulated MMP-7 levels in patients with carotid atherosclerosis, in particularly in those with the most recent symptoms, potentially related to the interaction between inflammation, modified lipids and ischemia/hypoxia within plaque monocytes/macrophages." (PMID 24400123, 2014). "In the present study, patients requiring carotid revascularization appeared with higher levels of CAVI, MMP-3, MMP-7 MMP-9, and TIMP-1 compared to patients with carotid atherosclerosis under conservative treatment or controls without carotid atherosclerosis." (PMID 37759829, 2023). "In conclusion, patients with established carotid atherosclerosis presented with exaggerated CAVI, MMP-3, MMP-7 MMP-9, and TIMP-1 levels compared to individuals without carotid atherosclerotic plaques." (PMID 37759829, 2023).
chronic pancreatitis (4 papers, 2013 to 2024). A chronic inflammatory process causing damage and fibrosis of the pancreatic parenchyma. "A second confirmatory phase on an independent cohort of 131 PDAC patients, 30 chronic pancreatitis patients, and 131 healthy subjects confirmed the PDAC association for MMP7, CCN2, IGFBP2, TSP2, sICAM1, TIMP1, and PLG." (PMID 29941541, 2018). "None of the three molecules were elevated in the plasma of mice with caerulein‐induced chronic pancreatitis after 7 weeks of treatments confirming the specific association of high levels of TIMP1, MMP7, and TSP2 with neoplastic transformation." (PMID 29941541, 2018). "The results indicated that median plasma MMP-7 levels were significantly higher in carcinoma than in cases with chronic pancreatitis, but the MMP-7 level in plasma alone is not sufficient as a positive predictive value." (PMID 32751899, 2020).
clear cell renal carcinoma (4 papers, 2013 to 2026). A malignant epithelial neoplasm of the kidney characterized by the presence of lipid-containing clear cells within a vascular network. "The matrixdegradation by invasive clear cell renal carcinoma cells is supportedby significant upregulation of genes, including MMP7 and MMP8, and downregulation of the key basement membraneprotein collagen IV (COL4) gene." (PMID 39398183, 2024). "This study assessed the expression and clinical significance of matrix metalloproteinase 7 (MMP-7) and tissue inhibitor of matrix metalloproteinases 2 (TIMP-2) in human clear cell renal cell carcinoma (CCRCC) by tissue microarray, immunohistochemistry and RT-PCR analysis." (PMID 23408109, 2013).
gastric ulcer (4 papers, 2010 to 2022). An ulcerated lesion in the mucosal surface of the stomach. "IHC has shown that H. pylori–related gastric ulcers express significantly higher levels of MMP-7, MMP-9 and TIMP-1 in comparison to undamaged tissue and NSAID (nonsteroidal anti-inflammatory drug)-related ulcer tissue." (PMID 35163805, 2022). "The findings indicate that H. pylori-infected gastric ulcers express higher MMP-7, MMP-9, and TIMP-1 compared to NSAID-related ulcers." (PMID 22645431, 2012). "H. pylori-infected gastric ulcers had even higher MMP-7, MMP-9, and TIMP-1 expressions in epithelial cells than NSAID-related gastric ulcers (P < 0.05)." (PMID 22645431, 2012). "Over superficial epithelium of gastric ulcer tissues, MMP-7, MMP-9, and TIMP-1 expressions were significantly lower in the NSAID-related group than in the H. pylori-infected group (P < 0.05)." (PMID 22645431, 2012). "A large-scale German survey has further validated that the single-nucleotide polymorphisms (SNP) genotype as MMP-7-181 G allele and MMP-9exon 6 A allele increase the risk of gastric ulcer after H. pylori infection." (PMID 20707923, 2010). "by working on 126 gastric ulcer patients showed that H. pylori-infected gastric ulcers had even higher MMP-7, MMP-9, and TIMP-1 expressions in epithelial cells compared to NSAID-related gastric ulcers." (PMID 35832384, 2022). "In patients with the two combined factors, gastric ulcers expressed similar proportions of antral ulcers and MMP-7 and MMP-9 intensities to NSAID-related gastric ulcers, but lower MMP-9 and TIMP-1 than H. pylori-infected gastric ulcers (P < 0.05)." (PMID 22645431, 2012). "MMP-7, MMP-9, and TIMP-1 expressions over the superficial epithelium of gastric ulcer tissues were higher than in nonulcer tissues (P < 0.05)." (PMID 22645431, 2012).
head and neck squamous cell carcinoma (4 papers, 2012 to 2023). A squamous cell carcinoma that arises from any of the following anatomic sites: lip and oral cavity, nasal cavity, paranasal sinuses, pharynx, larynx, and salivary glands. "MMP7, MMP9, MMP11, MMP12 and MMP13 were all up-regulated in head and neck squamous cell carcinoma." (PMID 36941602, 2023).
influenza (4 papers, 2008 to 2022). An acute viral infection of the respiratory tract, occurring in isolated cases, in epidemics, or in pandemics; it is caused by serologically different strains of viruses (influenzaviruses) designated A, B, and C, has a 3-day incubation period, and usually lasts for 3 to 10 days. "MMP7-/- mice were found to be more susceptible to PR/8 influenza infection." (PMID 28591220, 2017). "Smoke and influenza mice had increases in gene expression of MMP-7 at d3 only and of MMP-9 at d10 only." (PMID 18627612, 2008). "Gene activities of MMP7/9 migratory proteins are also upregulated in influenza infection." (PMID 35629310, 2022).
metastatic colorectal cancer (4 papers, 2014 to 2021). "IGFBP proteins are tightly regulated by serine proteases and matrix metalloproteinases, particularly matrix metalloproteinase-7 (MMP7), which is associated with poor prognosis in metastatic colorectal cancer (mCRC)." (PMID 34065119, 2021). "TIMP-1 and MMP-7 are highly sensitive and accurate diagnostic biomarkers for metastatic colorectal cancer." (PMID 34907282, 2021).
metastatic melanoma (4 papers, 2013 to 2025). A melanoma that has spread from its primary site to another anatomic site. "MMP-7 or matrilysin is expressed and produced by primary cutaneous and metastatic melanomas." (PMID 27271600, 2016). "Moreover they suggest that other MMPs (MMP7, MMP10, MMP11, and MMP13) might be implicated in CNS invasion by metastatic melanoma cells." (PMID 25692137, 2015). "Soluble ADAM9, MMP7 and OPN, analyzed in the conditioned media from control and miR-transduced metastatic melanoma cells, confirmed their miR-126&126*-dependent reduction (right)." (PMID 23437250, 2013).
multiple sclerosis (4 papers, 2009 to 2023). A progressive autoimmune disorder affecting the central nervous system resulting in demyelination. "Moreover, MMP-7 CSF level is associated with major depressive disorder, multiple sclerosis, and human immunodeficiency virus dementia." (PMID 34680129, 2021). "MMP-7 has also been linked to neuroinflammation with multiple sclerosis and depression." (PMID 28302163, 2017). "In the present study, we have examined proteolysis of N-cadherin (N-cdh) by MMP-7, a family member that has been implicated in disorders including HIV dementia, multiple sclerosis, and major depression." (PMID 28302163, 2017). "Finally, astrocyte cluster 8 (MMP7, SERPINA3, GZMA, and CLIC1) and microglial cluster 2 (DSG2 and TNFRSF25) were elevated in multiple sclerosis patients and suggested the pathogenic role of these biomarkers during multiple sclerosis progression." (PMID 37468977, 2023). "Our findings suggest that MMP-7 may facilitate immune cell access or re-stimulation in perivascular areas, which are critical events in EAE and multiple sclerosis, and provide a new therapeutic target to treat this disorder." (PMID 19267908, 2009).
myocardial infarction (4 papers, 2014 to 2025). Gross necrosis of the myocardium, as a result of interruption of the blood supply to the area, as in coronary thrombosis. "In mice, levels of fibronectin and of the ECM protein tenascin C, another MMP7 substrate, increase in response to myocardial infarction, but counterintuitively, this effect is less pronounced in MMP7 knockout mice." (PMID 40059514, 2025). "Meanwhile, recent studies showed that a variety of MMPs increase in the myocardium after myocardial infarction, including MMP-1, MMP-2, MMP-3, MMP-7, MMP-9, MMP-11, and so on." (PMID 25237357, 2014). "Additionally, doxycycline, an MMP inhibitor independent of its antimicrobial properties, has demonstrated efficacy in reducing MMP7 and MMP8 levels, thereby decreasing the systemic inflammatory burden and potentially preventing secondary myocardial infarctions." (PMID 40136525, 2025).
nasal polyps (4 papers, 2020 to 2024). "Previous studies provided evidence for higher levels of MMP‐1, MMP‐2, MMP‐3, MMP‐7, MMP‐8, and MMP‐9 in nasal polyps." (PMID 34504680, 2021). "Previous studies demonstrated that TGF-β1, MMP2, MMP7, and MMP9 could induce EMT in nasal polyps and can be synthesized and secreted by macrophages." (PMID 35990621, 2022). "Tissue protein analysis confirmed elevated levels of these targets compared to controls, and increased MMP3 and MMP7 observed in CRS subjects with nasal polyps compared to CRS subjects without polyps." (PMID 33005006, 2020).
pancreatitis (4 papers, 2018 to 2024). Inflammation of the pancreas. "A large number of studies have compared MMP7 expression in PDAC patients with pancreatitis patients and/or healthy controls and have consistently shown that MMP7 levels are elevated in PDAC patients." (PMID 32325664, 2020). "The effect of MMP7 on acinar-to-ductal metaplasia seems model-specific, however, as MMP7 deficiency did not affect pancreatitis driven-PanIN development in Pfta1-Cre Kras(G12D) mice." (PMID 32325664, 2020). "It has been shown that pancreatic acini from MMP7 knockout mice failed to undergo ADM in a pancreatitis model as well as in response to EGF activation." (PMID 38731942, 2024).